RAB7A (RAB7A, member RAS oncogene family)
Diseases named in the same sentence as RAB7A in open-access papers (continued):
Sharing a sentence is not in itself a finding about the gene and the disease.
Charcot-Marie-Tooth disease type 2B (6 papers, 2019 to 2022). Autosomal dominant Charcot-Marie-Tooth disease type 2B (CMT2B) is a severe form of axonal Charcot-Marie-Tooth disease, a peripheral sensorimotor neuropathy. "It was also observed that the Charcot-Marie-Tooth disease type 2B (CMT2B)-associated mutation of Rab7a impaired local protein synthesis, mitochondria function and axon integrity." (PMID 35450015, 2022). "A mutation in protrudin (ZFYVE27) has previously been identified in spastic paraplegia, while mutations in Rab-7a (RAB7A) have been identified in Charcot-Marie-Tooth type 2B neuropathy." (PMID 35227461, 2022). "Disruption of Rab7a function by expression of Charcot-Marie-Tooth disease type 2B (CMT2B)-linked Rab7a mutants leads to impaired local protein synthesis, mitochondrial dysfunction, and loss of axon integrity." (PMID 30612743, 2019). "Disruption of Rab7a function with Rab7a mutants, including those associated with Charcot-Marie-Tooth type 2B neuropathy, markedly decreases axonal protein synthesis, impairs mitochondrial function, and compromises axonal viability." (PMID 30612743, 2019). "Despite the fact that there is no direct demonstration of the coordination of these two GTPases on a specific disease, mutations of the RAB7A gene are responsible for the onset of Charcot-Marie-Tooth disease type 2B (CMT2B), a dominant axonal peripheral neuropathy." (PMID 31035701, 2019).
neuropathy (6 papers, 2013 to 2025). A disorder affecting the nervous system that manifests with pain, tingling, numbness, and/or muscle weakness. "Charcot–Marie–Tooth type 2B (CMT2B) is a peripheral ulcero-mutilating neuropathy caused by four missense mutations in the rab7a gene." (PMID 23179371, 2013). "Several monogenic disorders may be categorized as both defects in autophagy and vesicular trafficking, for instance RAB7A‐related neuropathy or TECPR2‐related spastic paraplegia." (PMID 39420677, 2025). "In contrast with these studies, work done on D. melanogaster suggested that CMT2B is a consequence of a partial loss-of-function of Rab7a, as expression of CMT2B mutants does not cause neuropathy-like phenotypes." (PMID 31426400, 2019).
Alzheimer disease (5 papers, 2011 to 2024). A progressive, neurodegenerative disease characterized by loss of function and death of nerve cells in several areas of the brain leading to loss of cognitive function such as memory and language. "C5orf51 was also identified in a GWAS study pertaining to Alzheimer’s disease, therefore highlighting the potential role of C5orf51 in Rab7A mediated mitophagy." (PMID 35392168, 2022). "The findings indicated that SIRT5 desuccinylated and activated RAB7A at the K31 residue to rescue the cadmium‐provoked Alzheimer's disease progression by restoring the autophagic flux, and identified potential targets for the treatment of environmental contaminant‐associated brain degeneration." (PMID 38837686, 2024). "Rab7A deletion on primary cortical neuronal cells and HeLa cells overexpressing Tau downregulated Tau secretion which clearly indicated the pathological role of Rab7A in Alzheimer’s disease and Tauopathy." (PMID 35006431, 2021).
viral infection (3 papers, 2019 to 2022). "On the other hand, silencing of RAB7A had a strong inhibitory effect on viral multiplication, reflecting the role of endosomal trafficking on viral infection outcome." (PMID 31216340, 2019).
Ataxia (2 papers, 2022 to 2023). Ataxia refers to impaired coordination of voluntary muscle movement. "Interestingly, mutations in the ATL1, SPAST, RAB7A or KATNB1 genes have been previously associated with diseases presenting with hyperreflexia, sensory axonal neuropathy or sensory impairment among other signs, which overlap with clinical signs identified in this new ataxia subtype in our family." (PMID 35310830, 2022).
autoimmune disease (2 papers, 2022 to 2023). A disorder resulting from loss of function or tissue destruction of an organ or multiple organs, arising from humoral or cellular immune responses of the individual to their own tissue constituents. "NOSTRIN connects to another nitric oxide gene, NOS3, RNF115 to the RAS oncogene family member RAB7A, while SPRR2A connects with EVPL (associated with squamous cell cancer and autoimmune disease)." (PMID 38030619, 2023). "MAPK signaling activated by Rab7a phosphorylation may be a response to post-infectious inflammation, and Rab7a may be a new target for the control of LPS/EGFR-mediated inflammation and autoimmune diseases." (PMID 36344490, 2022).
axonal neuropathy (2 papers, 2021 to 2022). Any nerve disorder affecting the axon of a nerve. "Charcot-Marie-Tooth type 2B (CMT2B) disease is a dominant axonal peripheral neuropathy caused by five mutations in the RAB7A gene." (PMID 35159308, 2022). "Mutations in the RAB7A gene cause the autosomal dominant Charcot–Marie–Tooth type 2B (CMT2B) disease, an axonal peripheral neuropathy." (PMID 32280996, 2021).
cervical carcinoma (2 papers, 2019 to 2020). A carcinoma arising from either the exocervical squamous epithelium or the endocervical glandular epithelium. "A recent review has highlighted the role of RAB7A protein in cancer progression, EV secretion and EV-mediated cisplatin resistance in ovarian and cervical cancer cells." (PMID 32384712, 2020). "It has been demonstrated in cervical carcinoma HeLa and in fibrosarcoma HT-1080 cells that endosomal trafficking and recycling of MT1-MMP1 are dependent on RAB7A and VAMP7." (PMID 31374919, 2019).
diabetes (2 papers, 2020 to 2022). "Here, we test the hypothesis that Rab7a inhibition can be used to increase growth factor receptor density in beta cells in order to enhance growth factor responses, and that this could be used to promote beta cell survival for the treatment of diabetes." (PMID 32978479, 2020). "Therapeutic Rab7a inhibition to maintain growth factor receptor density and subsequent growth factor responsiveness to protect islets may therefore be an effective approach to enable beta cells to survive the metabolic stress they are subjected to during diabetes pathogenesis." (PMID 32978479, 2020).
lung carcinoma (2 papers, 2019 to 2024). "This study reveals that except Rab7a, five Rab proteins, Rab8a, Rab11b, Rab27a, Rab35, and Rab37, were highly expressed in the purified AP of lung cancer cells (CL1‐5‐Q89L) with a high secretory tendency (Q) (column 4 vs. column 3)." (PMID 38804615, 2024). "Furthermore, RAB7A is able to regulate cell migration through Ras-related C3 botulinum toxin substrate 1 (RAC1) and vimentin in human lung cancer NCI H1299 cells." (PMID 31374919, 2019).
pancreatic cancer (2 papers, 2021 to 2022). "The results showed that there was a significant difference in overall survival (P = 0.004), progression-free interval (P = 0.004), and disease-specific survival (P = 0.001) between the pancreatic cancer patients in the high and low RAB7A expression groups." (PMID 36261459, 2022). "The results showed that RAB7A was moderately expressed in all normal pancreatic tissues and highly expressed in close to 75% of pancreatic cancer tissues." (PMID 36261459, 2022). "Our findings provide comprehensive evidence that high RAB7A expression is a poor prognostic factor in pancreatic cancer." (PMID 36261459, 2022). "We analysed the expression of RAB7A in all normal pancreatic tissues versus all pancreatic cancer tissues on the human protein atlas." (PMID 36261459, 2022). "The expression of RAB7A in normal pancreatic tissue was low to moderate, while it was highly expressed in pancreatic cancer." (PMID 36261459, 2022). "In pancreatic cancer patients with histological grade G1, RAB7A was expressed at relatively low levels." (PMID 36261459, 2022). "In addition, a series of experiments should be performed to investigate the regulatory mechanisms between RAB7A and the pancreatic cancer-related (e.g. MAPK, KRAS, PPAR) pathways screened by GSEA." (PMID 36261459, 2022). "Overall, RAB7A overexpression may serve as a biomarker for poor outcome in pancreatic cancer." (PMID 36261459, 2022). "RAB7A was expressed at significantly higher levels in pancreatic cancer patients who had not received radiation therapy than in those who had received radiation therapy." (PMID 36261459, 2022).
Parkinson's (2 papers, 2021 to 2024). "We next studied whether mutations equivalent to the common Parkinson's causing LRRK2 mutations would affect LRRK1's ability to phosphorylate Rab7A in cells." (PMID 33459343, 2021). "We identify two LRRK1 mutations (K746G and I1412T), equivalent to the LRRK2 R1441G and I2020T Parkinson's mutations, that enhance LRRK1 mediated phosphorylation of Rab7A." (PMID 33459343, 2021).
prostate carcinoma (2 papers, 2015 to 2018). A carcinoma that arises from epithelial cells of the prostate gland. "Other proteins enriched in prostate cancer proteins such as LAPTM4A, RAB7A, AFAP, and TSPAN6 are putative targets for CRL1 as detected by screening with a NEDD8 activating enzyme inhibitor." (PMID 26196085, 2015).
amoebiasis (1 paper, 2026). "In Entamoeba histolytica, the parasite that causes human amoebiasis, the retromer functions as a Rab7A GTPase effector and participates in phagocytosis and cytotoxicity." (PMID 42197362, 2026).
bipolar disorder (1 paper, 2020). A disorder of the brain that causes unusual shifts in mood, energy, activity levels and the ability to carry out day-to-day tasks. "Ras-related protein Rab-7a, Rho-associated protein kinase 2, and Exportin-7 were identified as potential peripheral protein candidates to distinguish major depressive disorder and bipolar disorder." (PMID 32245436, 2020).
breast invasive carcinoma (1 paper, 2024). "Together, these data provide valuable insights into the differential expression patterns of ITGB6, ERBB2, RAB5A, RAB7A, and GDI2 in breast invasive carcinoma." (PMID 39630893, 2024).
Charcot-Marie-Tooth disease (1 paper, 2020). An inherited degenerative disorder involving the peripheral nerves. "In addition, Rab endosomes are involved in sustaining mitochondria in axons, and the Rab7a mutation alters mitochondrial physiology and the anterograde axonal transport of mitochondria, contributing to Charcot Marie-Tooth disease." (PMID 33328904, 2020).
cholangiocarcinoma (1 paper, 2022). A carcinoma that arises from the intrahepatic biliary tree (intrahepatic cholangiocarcinoma) or from the junction, or adjacent to the junction, of the right and left hepatic ducts (hilar cholangiocarcinoma). "Several studies have shown increased expression of RAB7A in cholangiocarcinoma cells following the induction of epithelial–mesenchymal transition (EMT) and invasion by tumour necrosis factor-α (TNF-α) stimulation." (PMID 36261459, 2022).
cognitive decline (1 paper, 2024). "This activation of RAB7A served as a protective mechanism against autophagic flux blockade, ultimately mitigating the Cd‐induced exacerbation of AD‐like pathology and cognitive decline." (PMID 38837686, 2024).
colorectal cancer (1 paper, 2021). A primary or metastatic malignant neoplasm that affects the colon or rectum. "However, our data retrieved from the cBioPortal for Cancer Genomics database presented a significant positive relationship between MYOF and Rab7A in colorectal cancer." (PMID 33634965, 2021).
dementia (1 paper, 2023). Loss of intellectual abilities interfering with an individual's social and occupational functions. "Among the proteins, APOE, CLU, CHL1, SLC1A3, RAB7A, and CST3 were related to the protein aggregation of misfolded proteins—causative agents and symptomatic of neurodegenerative diseases—such as α-synuclein in PD, and amyloid-β and tau in dementia." (PMID 36797805, 2023).
depression (1 paper, 2020). "A previous study showed that RAB7A gene expression in the post-mortem brain was up-regulated in patients with depression who died by suicide." (PMID 32245436, 2020).
dissection (1 paper, 2025). The separation and isolation of tissues for surgical purposes, or for the analysis or study of their structures. "Rab-7a, involved in endocytosis and autophagy, regulates the phenotypic transformation and behavior of vascular smooth muscle cells in human aortic dissection." (PMID 40963926, 2025).
endotoxemia (1 paper, 2022). "In addition, phosphorylation of Rab7a promotes LPS-induced EGFR membrane expression, activated macrophages, and promotes lung tissue injury in mice with endotoxemia." (PMID 36344490, 2022).
gastric cancer (1 paper, 2024). A primary or metastatic malignant neoplasm involving the stomach. "Thus, Rab7a is e.g., associated with poor prognosis of gastric cancer and promotes proliferation, invasion, and migration of gastric cancer cells." (PMID 39562548, 2024).
glioblastoma multiform (1 paper, 2019). "Interestingly, CD44s interacts with RAB7A and blocks RAB7-mediated EGFR degradation by stimulating GTP hydrolysis in glioblastoma multiform cell lines." (PMID 31374919, 2019).
HIV-1 infection (1 paper, 2011). The type species of lentivirus and the etiologic agent of acquired immunodeficiency syndrome (AIDS). "Altogether, our results show that Rab7A is a key regulator in the late stages of the HIV-1 infection cycle, influencing several steps in the production and release of infectious viral particles." (PMID 22072966, 2011). "Moreover, cell surface expression of BST2 was not downregulated further upon HIV-1 infection in Rab7A knockdown cells (compare gate C2 to C1 on the upper 2nd panel)." (PMID 22072966, 2011).
ischemic stroke (1 paper, 2025). A stroke disorder caused by obstruction of blood flow to the brain, due to thrombotic (local blood clot formation) or embolic (due to a blood clot or other material traveling from another site) event. "To determine if Rab7a deletion in ECs impacts transcellular BBB permeability after ischemic stroke, we analyzed the leakage of endogenous serum immunoglobulin G (IgG) and a 70 kDa dextran-TMR administered intravenously at 48-hours post-t-MCAO." (PMID 41024170, 2025). "Thus, Rab7a elimination in BECs reduces acute structural abnormalities of BBB TJs after ischemic stroke also at the electron microscopy level." (PMID 41024170, 2025). "Rab7a activation is also critical to promote autophagy which together with the ubiquitin-proteasome system serve as two independent mechanisms to degrade and clear protein debris under cellular stress responses such as ischemic stroke." (PMID 41024170, 2025). "Therefore, pro-inflammatory cytokines likely mediate BBB TJ degradation at the acute phase of ischemic stroke through both Rab7a-dependent and -independent mechanisms." (PMID 41024170, 2025). "Two pro-inflammatory cytokines, TNFα and IL1β, that are known to trigger disruption of paracellular barrier properties in primary brain endothelial cells in vitro and are upregulated after ischemic stroke, contribute to Rab7a activation in primary mouse brain endothelial cells (BECs)." (PMID 41024170, 2025). "Yet, how endothelial Rab7a contributes to acute BBB dysfunction after ischemic stroke is unknown." (PMID 41024170, 2025). "Rab7a is, therefore, critical for degradation of select BEC junctional proteins during the acute increase in BBB permeability after ischemic stroke." (PMID 41024170, 2025). "In conclusion, our findings provide evidence for a new mechanism by which inflammatory cytokines promote degradation of select junctional proteins via Rab7a activation, leading to BBB dysfunction after ischemic stroke." (PMID 41024170, 2025). "Since ischemic stroke induces inflammation which exacerbates BBB disruption, we then tested whether distinct pro-inflammatory cytokines induce Rab7a activation." (PMID 41024170, 2025). "Here, we show that endothelial-specific deletion of Rab7a improves neuronal survival and reduces acute BBB disruption in mice after ischemic stroke by preventing degradation of some junctional proteins and preserving TJ morphology at both confocal and electron microscopy levels." (PMID 41024170, 2025). "Rab7a activation pushes the endolysosomal pathway towards degradation, rather than recycling, and drives cell junctional proteins toward the lysosomes which further exacerbates acute changes in paracellular BBB permeability after ischemic stroke." (PMID 41024170, 2025). "To understand how Rab7a affects the disassembly of BBB tight and adherens junctions during the acute phase of ischemic stroke, we analyzed the morphology of eGFP::Claudin-5+, ZO-1+ TJs and CDH5+ AJs at 48 hours after t-MCAO by immunofluorescence and electron microscopy." (PMID 41024170, 2025). "Overall, these data show that Rab7a elimination in BECs predominantly reduces ZO-1 degradation and localization to cell junctions compared to Claudin-5 or VE-Cadherin during the acute BBB damage after ischemic stroke." (PMID 41024170, 2025). "Thus, Rab7a EC-specific deletion did not affect the acute transcellular BBB leakage after ischemic stroke or the upregulation of Cav-1 protein." (PMID 41024170, 2025). "The mechanism by which Rab7a activation triggers degradation of BBB junctional proteins to promote disassembly of BEC cell junctions after ischemic stroke implies a potential lack of selectivity, since the endolysosomal degradation is a fundamental cell biological process." (PMID 41024170, 2025).
ischemic stroke (continued). "To determine if Rab7a may similarly mediate degradation of BBB TJ proteins in BECs after ischemic stroke, we generated a Rab7a-inducible EC knockout mouse strain [Rab7aiECKO(Rab7afl/fl; VEC-CreERT2+/−; eGFP::Claudin5+/−] to ablate Rab7a in ECs upon administration of 4-OH-tamoxifen." (PMID 41024170, 2025). "In summary, Rab7a EC-specific deletion rescues significantly the acute changes in paracellular, but not transcellular, BBB permeability after ischemic stroke." (PMID 41024170, 2025).
leukemia (1 paper, 2014). A malignant (clonal) hematologic disorder, involving hematopoietic stem cells and characterized by the presence of primitive or atypical myeloid or lymphoid cells in the bone marrow and the blood. "RAB7A has been shown to prevent growth factor-independent survival by inhibiting cell-autonomous nutrient transporter expression and the RAB7A gene is frequently rearranged in different types of leukemia." (PMID 25328887, 2014).
liver cirrhosis (1 paper, 2024). "The comparative analysis identified four platelet proteins, namely Ras-related protein Rab-7a (Rab-7a), Ran-specific binding protein 1 (RANBP1), Rho GDP-dissociation inhibitor 1 (RhoGDI1), and 14–3-3 gamma with progressively decreased protein expression in patients with liver cirrhosis." (PMID 38279183, 2024).
liver dysfunction (1 paper, 2022). "Similar to the effects of BafA1 or CQ, some natural products inhibit autophagosome–lysosome fusion by impairing the acidic environment of lysosome and decreasing the expression of fusion-related protein Rab7a, subsequently alleviating liver dysfunction." (PMID 36499429, 2022).
malaria (1 paper, 2012). Malaria is a serious and sometimes fatal disease caused by a parasite that commonly infects a certain type of mosquito which feeds on humans. "The results showed that, compared to the negative control, the live malaria parasite was able to induce an increase in the expression of Rab1a, Rab1b, Rab7a, Rab10, Rab14, Rab20, Rab27a, Rab32 and Rab38." (PMID 22911692, 2012).